PCNA (proliferating cell nuclear antigen)
Diseases named in the same sentence as PCNA in open-access papers (continued):
Sharing a sentence is not in itself a finding about the gene and the disease.
liver diseases (3 papers, 2007 to 2023). "In addition, high level of PCNA expression was found in the cells derived from human SSCs, which indicates that these cells had a strong proliferation capacity and offers an invaluable source of human hepatocytes for curing liver diseases." (PMID 28107194, 2017).
lung squamous cell carcinoma (3 papers, 2023 to 2025). "Finally, CDK1, PLK1, PCNA, ZWINT and NDC80 identified as hub genes for underlying molecular mechanisms of lung squamous cell carcinoma lymphatic metastasis." (PMID 37185598, 2023). "Finally, CDK1, PLK1, PCNA, ZWINT and NDC80 identified as hub genes for underlying molecular mechanisms of lung squamous cell carcinoma and lymphatic metastasis." (PMID 37185598, 2023). "For example, USP1 deubiquitinates FANCD2/FANCI or PCNA to prevent the recruitment of interstrand crosslink repair proteins and translesion DNA polymerase to inhibit DNA repair; USP7 regulates lung squamous cell carcinoma cell proliferation through MEK/ERK signaling by deubiquitinates the Raf-1." (PMID 37107644, 2023).
myoma (3 papers, 2021 to 2026). "The results of the study indicate that a good response to UPA, manifested by a volume reduction of myoma, may be associated with a decrease in fibrosis, ER/PR and PCNA and Ki67 immunoexpression and an increase in cell apoptosis within the myoma." (PMID 33546154, 2021). "The results of the study indicate that a good response to UPA, manifested by a volume reduction of myoma, may be associated with a decrease in fibrosis, ER/PR and PCNA and Ki67 immunoexpression as well as an increase in cell apoptosis in uterine myoma." (PMID 33546154, 2021). "It has also been reported that vitamin D inhibits uterine myoma cell growth through the downregulation of proliferating cell nuclear antigen and cyclin-dependent kinase 1 and the inhibition of COMT expression and activity." (PMID 33504114, 2021). "Also, it stimulates DNA and protein synthesis and cell proliferation in myoma cells, as well as activating collagen a1, PCNA production, and the MAPK pathway." (PMID 41514933, 2026).
nephritis (3 papers, 2017 to 2024). Inflammation of renal tissue. "In this study, we established Thy-1 rat nephritis models and administered 1.25(OH)2D3 and rapamycin to the experimental groups to observe changes in PCNA and mTOR expression in rat renal tissues at different time points." (PMID 39636964, 2024). "Our comprehensive analysis of the effects of 1.25(OH)2D3 on renal histopathology, mTOR protein, and PCNA in rat nephritis models showed that the grading of pathological renal damage, PCNA expression, and mTOR expression were positively correlated (p <0.05)." (PMID 39636964, 2024). "Per immunostaining results, induction of anti-Thy1.1 nephritis resulted in obvious infiltration of monocytes/macrophages and upregulated levels of α-SMA and PCNA in glomeruli, while MPA and CLT markedly downregulated these markers." (PMID 29026082, 2017). "PCNA was detected in 23.8% of SLE patients without Nephritis compared to 4.9% of patients with LN patients, a statistically significant variability with a P value of 0.026." (PMID 28819535, 2017).
odontogenic tumors (3 papers, 2016 to 2025).
oligodendroglioma (3 papers, 1997 to 2023). A well-differentiated (WHO grade II), diffusely infiltrating neuroglial tumor, typically located in the cerebral hemispheres. "We observe that different genes belonging to this pathway exhibit different trends, for example genes such as POLD1(chr19), RPA2(chr1), and LIG1(chr19) loose a copy in IDH-mut oligodendrogliomas, while genes RPA3(chr19), PMS2(chr19), PCNA(chr20) and POLD2(chr7) gain a copy in IDH-wt GBM." (PMID 36918656, 2023).
otitis media (3 papers, 2012 to 2022). Inflammation of the anatomical structures of the middle ear, which is most often caused by an infectious process. "The OM in Hyp-Duk/Y mice was characterised by effusion and/or mucosal cell proliferation indicated by increased goblet cell density and by PCNA staining, a marker of active cell proliferation that is associated with otitis media." (PMID 23028440, 2012). "PCNA, an active cell proliferation marker, was highly associated with otitis media." (PMID 36874359, 2022). "Staining for PCNA to label proliferating cells confirmed that the mutant ears with otitis media showed increased proliferation in the middle ear epithelium, particularly along the promontory at P21, while heterozygous ears without otitis media had very low levels similar to wild types." (PMID 36299576, 2022).
ovarian tumor (3 papers, 2009 to 2022). "The proliferative subtype was identified by the overexpression of transcription factors HMGA2 and SOX11, proliferation marker genes such as MCM2 and PCNA, and underexpression of MUC1 and MUC16, which are known ovarian tumor marker genes." (PMID 25611546, 2015).
pterygium (3 papers, 2011 to 2019). A wedge-shaped fibrovascular lesion arising from the bulbar conjunctiva and extending to the cornea. "We further investigated the expression of the proliferation related genes PCNA, CyclinD1 and P27 in pterygium and normal conjunctiva." (PMID 28779179, 2017). "In this study, we also invesgated the expression of the proliferation related genes PCNA, CyclinD1 and P27 in pterygium and normal conjunctiva." (PMID 28779179, 2017). "In agreement with findings from other studies, PCNA-positive cells were significantly increased in pterygium and western blot analysis of CyclinD1 and P27 confirmed the hyperproliferation characteristic of pterygium compared with normal conjunctiva." (PMID 28779179, 2017). "The results showed that positive-PCNA, mP53, and Bcl-2 rates were significantly increased in the pterygium samples compared to normal conjunctiva samples." (PMID 21738398, 2011). "The rates of positive PCNA were significantly higher in the pterygium samples than in the normal conjunctiva samples." (PMID 21738398, 2011). "Our study revealed that the positive rate of PCNA and Ki-67 significantly increased in the pterygium samples compared to the normal conjunctiva samples." (PMID 21738398, 2011). "In this study, we tested the expression of two proliferation markers (PCNA and Ki-67) and four apoptosis-related bio-markers (mP53, Bcl-2, Bax, and caspase-3) in pterygium and normal conjunctiva samples." (PMID 21738398, 2011). "In the present study, PCNA was expressed in 24 (72.7%) of the 33 pterygium samples, but in only 7 (30.4%) of the 23 normal conjunctiva samples." (PMID 21738398, 2011).
retinoblastoma (3 papers, 2014 to 2024). A malignant tumor that originates in the nuclear layer of the retina. "Nuclear PCNA staining was uniformly detected in the retinoblastoma nuclei whilst the adjacent retina remained quiescent." (PMID 27739525, 2016). "In both retinoblastoma cell lines, the levels of Bcl-2, CDK1 and PCNA were significantly upregulated in the PAX6 inhibition study groups than in negative GFP-control groups (Bcl-2, t=−5.90, P<0.05 and t=−4.86, P<0.05, resp." (PMID 24939714, 2014).
seminoma (3 papers, 2019 to 2025). A radiosensitive malignant germ cell tumor found in the testis (especially undescended), and extragonadal sites (anterior mediastinum and pineal gland). "This study investigates the immunolabeling of key iron-related proteins (Transferrin Receptor 1, Transferrin Receptor 2, and Ferritin Heavy chain 1) and Proliferating Cell Nuclear Antigen (PCNA) in canine SCO tubules within distinct microenvironments: seminomas, Sertoli cell tumors, and isolated." (PMID 40427255, 2025). "Interestingly, in CS, a peculiar PTMA and PCNA signals was seen: indeed, in the cytoplasm and the nucleus of some seminoma cells clusters, their intensity was evident (asterisks), while in others they were completely absent (dots)." (PMID 36139050, 2022). "In addition, proliferating cell nuclear antigen (PCNA) was expressed in most cells expressing CSE1L in the testis and seminoma tissues, indicating that CSE1L may be closely related to cell proliferation." (PMID 30485574, 2019).
skin cancer (3 papers, 2015 to 2025). "It is a safe agent preventing UVB-induced skin cancer via targeting inflammatory mediators (lowering COX-2, PGE2, PCNA, TNF-α, IL-1β, and IL-6 levels), cell cycle regulators (CDK inhibitor upregulation), and cell survival signals (cyclins D1, D2, E2 and CDKs2, 4, 6 inhibition)." (PMID 40943669, 2025). "PFD administered since the beginning of the photodamage induced by UVB irradiation showed an anti-inflammatory effect, low expression of epidermal PCNA and the absence of skin tumors." (PMID 37049691, 2023).
Ureteral obstruction (3 papers, 2017 to 2021). Obstruction of the flow of urine through the ureter. "Increased PCNA expression was found at 24 h after ureteral obstruction." (PMID 28904080, 2017). "Finally, we examined PCNA expression in vivo at 24 h following ureteral obstruction." (PMID 28904080, 2017). "Previously, we showed that 10 days after unilateral ureteral obstruction (UUO), high expression of proliferating cell nuclear antigen (PCNA) appeared in the RTECs of the contralateral kidney accompanied by ECM deposition." (PMID 34386059, 2021).
Uterine leiomyoma (3 papers, 2015 to 2017). The presence of a leiomyoma of the uterus. "Also, uterine leiomyoma in the EKER rat showed much higher proliferation indices in comparison to human UFs, as determined by PCNA stain." (PMID 26588841, 2015).
xeroderma pigmentosum (3 papers, 2016 to 2019). Xeroderma pigmentosum (XP) is a rare genodermatosis characterized by extreme sensitivity to ultraviolet (UV)-induced changes in the skin and eyes, and multiple skin cancers. "The NER process needs the participation of many proteins, such as Xeroderma pigmentosum (XP) complementation Groups A through G, excision repair cross-complementation group 1 (ERCC1), and proliferating cell nuclear antigen (PCNA)." (PMID 31546657, 2019).
adenomyosis (2 papers, 2021 to 2023). The growth of endometrial tissue inside the muscular wall of the uterine corpus. "At the same time, compared with the adenomyosis group, the expression of Bcl2 was decreased, the expression of Bax was increased, and Bcl2/Bax was decreased, while the expression of PCNA was decreased in the verteporfin group." (PMID 36940085, 2023). "The level of PCNA positive staining in the uterine tissue of adenomyosis mice was significantly higher than that of control mice." (PMID 36940085, 2023). "Our results indicated that the levels of CB1 and PCNA were increased in patients with adenomyosis and that cyclic changes were lost." (PMID 33531043, 2021).
adrenocortical cancer (2 papers, 2008 to 2017). "Or when the expression of FHIT is weakly positive, Ki-67 and PCNA is both strongly positive, adrenocortical carcinoma is suggested, too." (PMID 18366613, 2008). "Found in this study, expression level of PCNA in adrenocortical carcinoma is the highest, and expression level in adrenocortical hyperplasia is the lowest." (PMID 18366613, 2008). "On the contrary, expression levels of tumor proliferation cell nuclear antigens Ki-67 and PCNA are roughly proportional to the cell proliferating degree, their levels of expressions in adrenocortical carcinoma are high and in adrenocortical hyperplasia are low." (PMID 18366613, 2008). "When the expression of FHIT is negative but both of Ki-67 and PCNA are strongly positive, adrenocortical carcinoma is suggested." (PMID 18366613, 2008).
Allergy (2 papers, 2016 to 2021). An allergy is an immune response or reaction to substances that are usually not harmful. "This analysis showed that the number of PCNA+ proliferating cells in the dentate gyrus was not changed in the allergy model (control: 1579 ± 223 cells per hemisphere; allergy: 1606 ± 179 cells per hemisphere; p < 0.7847)." (PMID 27445696, 2016).
Anxiety (2 papers, 2023 to 2024). Intense feelings of nervousness, tension, or panic often arise in response to interpersonal stresses. "In both studies, BCI-838 treatment increased brain levels of markers of neurogenesis (BrdU, DCX, PCNA), reduced anxiety-related behaviors, and reversed learning behavior deficits." (PMID 39081972, 2023).
Arthritis (2 papers, 2010 to 2014). Inflammation of a joint. "Anti-PCNA antibodies are present in 5–10% of SLE patients especially those with arthritis and hypocomplementemia." (PMID 24649358, 2014). "In WT mice with chronic SCW-induced arthritis, the number of proliferating cells detected was 219±52 PCNA-positive cells ± SEM per high-power field which was further reduced in IL-17R −/− mice compared to WT mice (110±15)." (PMID 20976214, 2010).
atrophic gastritis (2 papers, 2011 to 2017). "Our results revealed that cell proliferation in gastric glands was increased in rats with experimental atrophic gastritis, as determined by two of biomarkers, PCNA and GS II." (PMID 21949663, 2011). "The areas of PCNA stain were obviously enlarged in atrophic gastritis glands relative to normal stomach." (PMID 21949663, 2011). "To assess the cell proliferation in gastric glands of atrophic gastritis rats, we performed immunohistochemistry stains of PCNA and GS II in gastric tissues." (PMID 21949663, 2011).
breast ductal carcinoma (2 papers, 2016 to 2020). "CQ at a daily dose of 150 mg was able to reduce the proliferating cell nuclear antigen (PCNA) index in breast ductal carcinoma." (PMID 32410999, 2020).
cataract (2 papers, 2018 to 2022). Partial or complete opacity of the crystalline lens of one or both eyes that decreases visual acuity and eventually results in blindness. "Hyperproliferation in cataracts was assessed by detecting the cell proliferation marker PCNA in the lens by immunohistochemistry." (PMID 29888254, 2018).
cerebral infarction (2 papers, 2013 to 2022). An ischemic condition of the brain, producing a persistent focal neurological deficit in the area of distribution of the cerebral arteries. "The cerebral infarction area, the intima to media area (I/M ratio), and proliferating cell nuclear antigen (PCNA)-staining of the carotid artery were measured." (PMID 36361610, 2022). "Cerebral infarction area, ratio of intima to media area (I/M ratio) and PCNA antibody staining of the carotid artery in vivo were measured." (PMID 24086601, 2013). "TriL (50, 100, and 200 mg/kg, p.o.)reduced: the cerebral infarction area; neurological deficit; TUNEL-positive apoptosis; intimal hyperplasia; and PCNA-positive cells in rodents." (PMID 36361610, 2022). "PIPO (10 and 30 mg/kg p.o.)reduced: the cerebral infarction area; neurological deficit; TUNEL-positive cells; cleaved caspase 3-positive cells; intimal hyperplasia; and inhibited proliferating cell nuclear antigen (PCNA)-positive cells in rodents." (PMID 24086601, 2013).
cervical squamous cancer (2 papers, 2021 to 2023). "The results showed that compared with the control group of cervical squamous cell carcinoma SiHa cells, the expression of differential proteins PCNA, ATM, LIG1 and HMGB1 in Ect1/E6E7 cells decreased significantly, while the expression of TDG and OGG1 proteins increased significantly." (PMID 36726132, 2023). "Similarly, in SiHa cervical squamous cancer cells, RAGE-dependent activation of the PI3K/Akt signaling pathway has been shown to promote cell cycle progression through the upregulation of the proliferating cell nuclear antigen (PCNA)." (PMID 34360919, 2021).
cholesteatoma (2 papers, 2013 to 2021). A pathologic process characterized by the proliferation of keratinizing squamous epithelium resulting in the accumulation of keratin and cells in the middle ear and/or mastoid. "The most prominent pathogenic manifestation of a cholesteatoma, the hyperproliferative cholesteatoma epithelium, exhibits a high rate of Ki-67 and proliferating cell nuclear antigen positive cells compared to normal auditory skin." (PMID 33627146, 2021). "The positive rate of p-EGFR, p-Akt, cyclinD1, and PCNA expression was significantly increased in cholesteatoma epithelium (65.0%, 72.5%, 62.5%, and 80.0%, resp)." (PMID 24311896, 2013). "The expressions of p-EGFR, p-Akt, cyclinD1, and PCNA in cholesteatoma epithelium were significantly increased when compared with those of control subjects." (PMID 24311896, 2013). "We examined the expressions of phosphorylated EGF receptor (p-EGFR), phosphorylated Akt (p-Akt), cyclinD1, and proliferating cell nuclear antigen (PCNA) in 40 cholesteatoma samples and 20 samples of normal external auditory canal (EAC) epithelium by immunohistochemical method." (PMID 24311896, 2013). "In cholesteatoma epithelium, a significant positive correlation was observed between p-EGFR and PCNA expression and between the expressions of p-Akt and PCNA, cyclinD1, and PCNA, respectively (P < 0.01)." (PMID 24311896, 2013). "In addition, we compared the proliferative capacity of cholesteatoma epithelium with that of normal EAC epithelium, using PCNA as a proliferation marker." (PMID 24311896, 2013). "Moreover, in cholesteatoma epithelium, we demonstrated that a significant positive correlation was observed between p-EGFR and PCNA expression and between the expression levels of p-Akt and PCNA, cyclinD1 and PCNA, respectively." (PMID 24311896, 2013).
cognitive decline (2 papers, 2024 to 2025). "Some significant observations of the current study are the fact that the PCNA and BDNF expression in the MP groups increased, which suggests the presence of DNA lesions and a possible cognitive decline, whereas in terms of inflammation, it was present in all groups besides the control." (PMID 39125900, 2024).
colon adenoma (2 papers, 2011 to 2016). An adenoma that arises from the colon. "Tumors developed in both WT and Sesn2-/- mice displayed classical characteristics of colon adenomas, such as nuclear β-catenin staining, increased cell proliferation (PCNA staining), DNA damage (γ-H2AX staining) and apoptotic cell death (TUNEL staining)." (PMID 26913956, 2016). "Moreover, the development of colonic adenomas was increased remarkably in 50% of the tested rats together with the proliferation markers, namely the polyamine content and the proliferating cell nuclear antigen PCNA." (PMID 21247505, 2011).
dementia (2 papers, 2014 to 2017). Loss of intellectual abilities interfering with an individual's social and occupational functions. "As with PCNA, the difference in the number of marked cells seems to be even greater in patients with dementia: 76.5 ± 0.75 cells/500 μm2." (PMID 28874134, 2017). "PCNA+ profiles were never observed in mature neurons or GFAP+ astrocytes, indicating that these cell types do not proliferate or reenter the cell cycle during dementia or AD." (PMID 25215243, 2014).
Ehrlich tumor (2 papers, 2019 to 2023).